PCDH17 (protocadherin 17)
Diseases named in the same sentence as PCDH17 in open-access papers (continued):
Sharing a sentence is not in itself a finding about the gene and the disease.
mood disorder (3 papers, 2018 to 2020). A cognitive disorder a disturbance in which the person's mood is hypothesized to be the main underlying feature. "Accordingly, single-nucleotide polymorphisms (SNPs) in PCDH17 gene were found associated with mood disorders." (PMID 33352832, 2020). "In amygdala, the enhanced expression of PCDH17 has been associated to an increased risk to develop major mood disorders, including bipolar disorder, as observed in postmortem brains of patients with higher PCDH17 mRNA levels." (PMID 33352832, 2020). "Single-nucleotide polymorphisms (SNPs) spanning the PCDH17 region were found to be associated with mood disorders across multiple independent samples." (PMID 28070120, 2018). "Collectively, these data suggest that the PCDH17 rs9537793 not only associates with clinical diagnosis of major mood disorders, but also affects the specific intermediate phenotypes." (PMID 28070120, 2018). "Here, we present data from independent large-scale clinical data sets (including 29 557 cases and 32 056 controls) revealing brain expressed protocadherin 17 (PCDH17) as a susceptibility gene for major mood disorders." (PMID 28070120, 2018). "Here, we conduct a meta-analysis of independent clinical samples including a total of 29 557 cases and 32 056 controls and we report a novel risk candidate gene PCDH17 for major mood disorders." (PMID 28070120, 2018). "Collectively, these studies not only reveal that alterations in the levels of PCDH17 cause changes in dendritic spine morphology and abnormal synapse development, which underlie mood disorders, but also that the levels of PCDH17 are crucial for the risk to develop a disease state." (PMID 33352832, 2020). "In addition to major mood disorders, PCDH17 is also implicated in a previous schizophrenia study, in which PCDH17 was significantly increased in the brain of schizophrenia patients." (PMID 28070120, 2018). "Notably, the identification of PCDH17 as a susceptibility gene for major mood disorders is also consistent with a prior report of another cadherin gene (FAT) as a potential risk locus for BPD." (PMID 28070120, 2018). "The discovery of PCDH17 in the risk of mood disorders may also have therapeutic implications." (PMID 28070120, 2018). "In particular, the enrichment along the amygdala neurons and the basal ganglia synapses has made PCDH17 particularly interesting for its potential implications in mood disorders." (PMID 33352832, 2020). "Exploring the potential effects of elevated PCDH17 levels on the morphology and density of dendritic spines has noteworthy implications for both normal brain function and the pathophysiology of mood disorders." (PMID 28070120, 2018). "These convergent results implicate PCDH17 in the biology of synapses and in the etiology and pathophysiology of major mood disorders, making it a potential new target for the pharmacotherapy of these conditions." (PMID 28070120, 2018). "Among those protocadherin family members, PCDH17 (protocadherin 17) is expressed by a subset of amygdala neurons, and PCDH17 knockout mice exhibit antidepressant–like phenotypes, implying potential involvement of PCDH17 in major mood disorders." (PMID 28070120, 2018). "Changes in PCDH17 and PCDH15 have been implicated in mood disorder onset." (PMID 33352832, 2020). "These convergent lines of evidence suggest PCDH17 is a plausible susceptibility gene for major mood disorders, but direct evidence of association is still absent." (PMID 28070120, 2018).
schizophrenia (3 papers, 2016 to 2021). A major psychotic disorder characterized by abnormalities in the perception or expression of reality. "For example, PCDH10 mutations have been linked to autism, PCDH12 mutations have been associated with schizophrenia and microcephaly and seizures, and PCDH17 mutations have been involved in the pathogenesis of schizophrenia." (PMID 34201522, 2021). "Protocadherin 17 was detected during development of the nervous system in humans, and its dysfunction was linked to schizophrenia." (PMID 27351130, 2016).
bipolar disorder (2 papers, 2018 to 2020). A disorder of the brain that causes unusual shifts in mood, energy, activity levels and the ability to carry out day-to-day tasks. "The risk allele predicted higher transcriptional levels of PCDH17 mRNA in postmortem brain samples, which is consistent with increased gene expression in patients with bipolar disorder compared with healthy subjects." (PMID 28070120, 2018).
breast tumors (2 papers, 2016 to 2022). "Expression of PCDH17 was repressed in 89% (32/36) of breast tumor tissue samples, indicating that a loss of PCDH17 expression could lead to breast tumorigenesis." (PMID 27351130, 2016). "Annexin V-FITC/PI staining results indicated that PCDH17 has a pro-apoptotic effect on breast tumor cells (p < 0.001)." (PMID 27351130, 2016). "We found that PCDH17 was frequently downregulated or silenced in 78% (7/9) of breast tumor cell lines, as well as 89% (32/36) of primary tumors." (PMID 27351130, 2016). "Ectopic expression of PCDH17 in breast tumor cells inhibited cell proliferation and mobility through arresting cell cycle and inducing apoptosis." (PMID 27351130, 2016). "PCDH17 expression was markedly repressed in seven of the nine breast tumor cell lines tested, and weakly expressed in BT549, YCC-B3 and Sk-BR-3 cell lines." (PMID 27351130, 2016). "Taken together, these results indicate that PCDH17 is a functional TSG in breast tumor pathogenesis." (PMID 27351130, 2016). "In breast tumor cells, PCDH17 significantly suppressed the active β-catenin level and its downstream target gene expression." (PMID 27351130, 2016). "Immunohistochemistry results showed that protein expression levels of PCDH17 in breast tumor tissues were repressed in 89% (32/36) of cases, in comparison with those seen in normal tissues (p < 0.01)." (PMID 27351130, 2016). "We used methylation-specific PCR (MSP) to analyze PCDH17 promoter methylation status in nine breast tumor cell lines." (PMID 27351130, 2016). "Ectopic expression of PCDH17 suppressed the colony formation abilities of breast tumor cells (MB231 and MCF7), with an approximate 50–60% reduction in colony numbers in comparison with cells transfected with control vectors." (PMID 27351130, 2016). "Methylation of the PCDH17 promoter was observed in seven of the nine breast tumor cell lines, which was consistent with its low expression or absence." (PMID 27351130, 2016). "MSP and bisulfite sequencing revealed that PCDH17 promoter methylation was partially responsible for its downregulation in breast tumor cells." (PMID 27351130, 2016). "We examined expression levels of PCDH17 in breast tumor cell lines, normal breast tissue samples, and breast tumor samples using semi-quantitative RT-PCR, quantitative real-time PCR (qPCR) and immunohistochemistry analysis." (PMID 27351130, 2016). "In summary, we found that PCDH17 expression is frequently repressed, or silenced, in breast tumor cell lines when its promoter is methylated." (PMID 27351130, 2016). "The average mRNA expression level of PCDH17 in 18 breast tumor samples was significantly decreased compared with normal tissues (p < 0.05)." (PMID 27351130, 2016). "The biological functions of PCDH17 in breast tumor cells were assessed using in vitro and in vivo assays." (PMID 27351130, 2016). "We observed that PCDH17 was methylated in 93.3% (97/104) of primary breast tumor tissues, and 25% (4/16) of normal breast tissues." (PMID 27351130, 2016). "We confirmed that ectopic expression of PCDH17 resulted in the arrest of cell cycle, and the induction of cell apoptosis in breast tumor cells." (PMID 27351130, 2016). "We also investigated PCDH17 promoter methylation in breast tumor tissues." (PMID 27351130, 2016). "Therefore, we investigated PCDH17 expression levels and the methylation status of its promoter in breast tumor cell lines and primary tissues, as well as its biological functions in breast tumorigenesis." (PMID 27351130, 2016). "We further confirmed the suppression of PCDH17 on breast tumor cell proliferation and metastasis." (PMID 27351130, 2016). "We observed that PCDH17 were reduced in breast tumor cell lines and primary tumor samples." (PMID 27351130, 2016). "PCDH17 also suppressed β-catenin activity in breast tumor cells, although the molecular mechanism remains unknown and requires further investigation." (PMID 27351130, 2016).
breast tumors (continued). "In addition, the PCDH17 promoter was frequently methylated in breast tumors." (PMID 27351130, 2016). "PCDH17 is frequently downregulated and meantime hypermethylated in various human carcinomas; it is considered a TSG, and its biological function in tumour pathogenesis was discovered at first in breast tumour cell lines." (PMID 35409379, 2022).
diabetic cardiomyopathy (2 papers, 2019 to 2020). Diabetic cardiomyopathy is a disorder of the heart muscle in people with diabetes. "Former volumes reported that PCDH17 was up‐regulated in vascular smooth muscle cells of myocardial infarction, and was verified to promote cardiomyocyte autophagy in diabetic cardiomyopathy, indicating the relation between PCDH17 and heart disease." (PMID 32436661, 2020). "Also, in diabetic cardiomyopathy (DCM), lncRNA DCRF can up-regulate PCDH17 expression through sponging miR-551b-5p, leading to increased cardiomyocyte autophagy in DCM." (PMID 31827399, 2019).
esophageal cancer (2 papers, 2021 to 2025). A primary or metastatic malignant neoplasm involving the esophagus. "PCDH17 exhibited distinct patterns of expression across different tumor types, with upregulated expression observed in breast, cholangiocarcinoma, colon, and esophageal cancers." (PMID 40487760, 2025).
leukaemia (2 papers, 2019 to 2022). "In this respect, epigenetic modulation of miR-196b, an oncogenic miRNA discovered in many human malignancies and targeting PCDH17 mRNA was seen in human leukaemia cells." (PMID 35409379, 2022). "Our results showed that decreased PCDH17 expression was associated with female sex, higher median WBC counts, as well as higher median PB and BM blast counts, indicative of a high proliferative potential of PCDH17 repressed leukemia cells." (PMID 30922328, 2019).
myocardial infarction (2 papers, 2020 to 2022). Gross necrosis of the myocardium, as a result of interruption of the blood supply to the area, as in coronary thrombosis. "Protocadherin 17 (PCDH17) was reported to aggravate myocardial infarction." (PMID 32436661, 2020). "A Study about myocardial infarction revealed overexpression of CDH2, CDH12, PCDH17, and PCDH18 in myocardial infarction vascular smooth muscle cells compared with controls." (PMID 35480311, 2022).
ovarian carcinoma (2 papers, 2023 to 2025). A malignant neoplasm originating from the surface ovarian epithelium. "More research on PCDH17 in ovarian cancer is still needed to verify our findings as well as those of Baranova and her colleagues." (PMID 36698136, 2023). "We conclude that PCDH17 gene promoter hypermethylation has a potential role in diagnosis of epithelial ovarian cancer." (PMID 36698136, 2023). "The methylation of PCDH17 gene promoter has been described in several cancers including ovarian cancer." (PMID 36698136, 2023). "This emphasizes the relative importance of PCDH17 gene promoter hypermethylation in ovarian cancer diagnosis." (PMID 36698136, 2023). "The aim of the study was to compare the methylation status of PCDH17 gene promoter between females diagnosed with epithelial ovarian cancer and a control group composed of normal and benign ovarian lesions." (PMID 36698136, 2023). "PCDH17 gene promoter hypermethylation has been described to be found in different cancers other than ovarian cancer." (PMID 36698136, 2023). "In addition to this, using the PCDH17 methylation pattern in cf-DNA would increase our understanding of the usefulness of PCDH17 in ovarian cancer diagnosis and screening." (PMID 36698136, 2023). "PCDH17 promoter hypermethylation has been reported in ovarian cancer." (PMID 36698136, 2023). "Therefore, the purpose of this study was to assess the methylation status of PCDH17 gene promoter in epithelial ovarian cancer patients." (PMID 36698136, 2023).
acute lymphoblastic leukemia (1 paper, 2019). Leukemia with an acute onset, characterized by the presence of lymphoblasts in the bone marrow and the peripheral blood. "Indeed, a recent finding in pediatric acute lymphoblastic leukemia has shown that PCDH17 methylation was significantly associated with disease relapse and worse outcome, thereby suggesting a potential involvement of PCDH17 in leukemogenesis." (PMID 30922328, 2019).
Ataxia (1 paper, 2019). Ataxia refers to impaired coordination of voluntary muscle movement. "It is therefore likely that the increased level of Pcdh17 transcription in Dot1l-cKOAtoh1 resulted in synaptic impairment involved in the ataxia observed in these mice." (PMID 30302725, 2019).
bladder tumor (1 paper, 2019).
cervical cancer (1 paper, 2025). A primary or metastatic malignant neoplasm involving the cervix. "Conversely, decreased expression of PCDH17 was noted in cervical cancer, renal clear cell carcinoma, squamous cell lung cancer, and pancreatic cancer." (PMID 40487760, 2025).
diffuse large B-cell lymphoma (1 paper, 2024). "In dogs with diffuse large B-cell lymphoma, a lower expression of the PCDH17 gene was also observed in the cell culture of this neoplasm, which was related to the hypermethylation of this tumor suppressor gene." (PMID 39057100, 2024).
endothelial dysfunction (1 paper, 2023). In vascular diseases, endothelial dysfunction is a systemic pathological state of the endothelium (the inner lining of blood vessels) and can be broadly defined as an imbalance between vasodilating and vasoconstricting substances produced by (or acting on) the endothelium. "Therefore, we examined the effect of OXA on endothelial cells and found no detectable impact on genes associated with endothelial dysfunction and vascular injury, including Fabp4, Pcdh17, Esm1, and Cd34." (PMID 37697332, 2023).
glioma (1 paper, 2010). A benign or malignant brain and spinal cord tumor that arises from glial cells (astrocytes, oligodendrocytes, ependymal cells). "Among these, CDH13, TIAM1 and PCDH17 were up- and FLRT1 and OPCML down-regulated, thus indicating that the invasion capacity of glioma cells can be altered by cisplatin treatment." (PMID 21637621, 2010).
head and neck cancer (1 paper, 2017). A primary or metastatic malignant neoplasm affecting the head and neck. "The PCDH10 and PCDH17 promoter regions are reported to be hypermethylated in uterine cervical cancer, head and neck cancer, and some gastrointestinal cancers." (PMID 29075151, 2017).
liver cancer (1 paper, 2022). An epithelial or non-epithelial malignant neoplasm that arises from the liver. "Several studies have shown that PCDH genes are also involved in liver cancer development, including PCDH10, PCDH17, PCDH19, PCDH20, PCDHGC4, and PCDHGC5." (PMID 36230503, 2022).
pancreatic cancer (1 paper, 2025). "In pancreatic cancer, high PCDH17 expression associates with elevated inflammatory factors (TGF-β, IL6-JAK-STAT3, TNFA pathways) and enhanced immune activity, including antigen presentation and T-cell recruitment." (PMID 40487760, 2025). "The investigation of the tumor microenvironment in pancreatic cancer unveiled a noteworthy association between PCDH17 and T-cell infiltration." (PMID 40487760, 2025). "Additionally, we comprehensively examined the association between PCDH17 and immune cell infiltration as well as immunotherapy in pancreatic cancer." (PMID 40487760, 2025). "However, the underlying mechanism of PCDH17 in pancreatic cancer remains elusive." (PMID 40487760, 2025). "PCDH17 exhibits potential as a target for regulating the immune-suppressive tumor microenvironment in pancreatic cancer." (PMID 40487760, 2025). "The high and low PCDH17 groups displayed significant variations in the scores of multiple tumor-related pathways, suggesting that PCDH17 plays a role in the progression of pancreatic cancer tumors." (PMID 40487760, 2025). "PCDH17 exhibited predominant expression in endothelial cells within the tumor microenvironment of pancreatic cancer, while its expression was nearly negligible in immune cells." (PMID 40487760, 2025). "Additionally, as endothelial cells underwent differentiation within the tumor microenvironment of pancreatic cancer, there was a further decline in PCDH17 expression." (PMID 40487760, 2025). "Reduced expression of PCDH17 was observed in pancreatic cancer tissues." (PMID 40487760, 2025). "Moreover, the single-cell data of pancreatic cancer was utilized for analyzing PCDH17 expression, cell differentiation, and intercellular communication." (PMID 40487760, 2025). "Consequently, PCDH17 exhibits potential as a target for regulating the immune-suppressive tumor microenvironment in pancreatic cancer." (PMID 40487760, 2025). "The expression of inflammatory factors was found to be significantly elevated in the PCDH17 high-expression group compared with the PCDH17 low-expression group, suggesting a role for PCDH17 as an anti-inflammatory regulator within the tumor microenvironment of pancreatic cancer." (PMID 40487760, 2025). "We present, for the first time, evidence of the involvement of PCDH17 in modulating the non-inflammatory tumor microenvironment in pancreatic cancer." (PMID 40487760, 2025). "This study aims to elucidate the precise mechanism by which PCDH17 modulates the non-inflammatory tumor microenvironment in pancreatic cancer." (PMID 40487760, 2025).
serous ovarian carcinoma (1 paper, 2023). "In addition, the same group recently investigated PCDH17 gene methylation (with other genes namely CDH13, HNF1B and GATA4) in high grade serous ovarian carcinoma." (PMID 36698136, 2023).
urinary system tumors (1 paper, 2021). "They proposed that combined detection of TCF21 level and PCDH17 methylation is conductive to diagnose urinary system tumors." (PMID 34970358, 2021).
urothelial bladder cancers (1 paper, 2019). "However, little is known about the role of PCDH17 in urothelial bladder cancers." (PMID 31772653, 2019).
viral infections (1 paper, 2021). "Most importantly, one of this candidates, CHEMBL2007613, was predicted as a potential antiviral due to its involvement on the PCDH17 pathway, which has been reported to be related to viral infections." (PMID 33901196, 2021).